PPARA (peroxisome proliferator activated receptor alpha)
Diseases named in the same sentence as PPARA in open-access papers (continued):
Sharing a sentence is not in itself a finding about the gene and the disease.
Insulin resistance (continued). "The PPARα-mediated induction of TRB3 was proposed to suppress insulin action, to induce insulin resistance, and subsequently to promote gluconeogenesis." (PMID 20936117, 2010). "Furthermore, JLD activates AMPK to protect β-cells and stimulates the PPARα/ABCA1 pathway, thereby improving glucose–lipid metabolism, reducing hepatic lipid deposition, and alleviating insulin resistance." (PMID 41334442, 2025). "Moreover, PPARα activation improves hepatic lipid metabolism in HFD-fed mice, alleviating hepatic lipid deposition and insulin resistance." (PMID 39942052, 2025). "In addition, by upregulating the transcription of Cpt1a, Pparα, Mcad, Acsl, and Ppargc1a, it has been demonstrated that fexaramine, an agonist of FXR, contributes to alleviating insulin resistance and lipid accumulation in NAFLD mice." (PMID 40243350, 2025). "The experimental validation was confined to the AMPK signaling pathway and did not encompass the other prediction pathways, such as insulin resistance and PPARα." (PMID 40873448, 2025). "This improvement in insulin resistance is believed to result from enhanced beta oxidation, which is facilitated by elevated expressions of HSL and PPARα, as well as the augmented anti-inflammatory and antioxidant effects due to elevated levels of taurine and glycine." (PMID 38892554, 2024). "Based on the attenuation of fat accumulation in BAT and liver and the improvement of insulin resistance, we investigated the mtDNA copy number and the expression of lipid β-oxidation proteins in BAT, including PPARα, ACOX1, CPT1, and lipolysis proteins such as ATGL in BAT." (PMID 38576483, 2024). "In the present study, we inferred that whey protein intake enhances the reduction of visceral fat and improves insulin resistance by increasing the expression of PPARα and HSL, promoting β-oxidation of fatty acids in the liver, and leveraging the anti-inflammatory effects of PPARα itself." (PMID 38892554, 2024). "Activation of PPARα expression by KLF16 could improve steatohepatitis and insulin resistance through ROS reduction." (PMID 36589809, 2022). "These actions were parallel to reduced insulin resistance, improved mitochondrial respiration, mitochondrial oxidative capacity, and fatty acid oxidation, with effective regulation of prominent energy regulation markers such as AMPK, Pparα, and UCP2." (PMID 34068459, 2021). "While exhibiting some features of insulin resistance, PerIRKO+/− mice display a hepatic energy deficit accompanied by induction of energy-sensing AMPK, mitochondrial biogenesis, PPARα, unexpectedly leading to protection from, and reversal of hepatic lipid accumulation (steatosis hepatis, NAFLD)." (PMID 32350271, 2020). "The results showed that insulin resistance was decreased by 20% and in skeletal muscle the expression of PPARα and LPL mRNA increased; however, GLUT4 mRNA did not increase." (PMID 30691224, 2019). "Insulin resistance should have different effects on FXR and PPARα." (PMID 24260557, 2013). "The mechanism of this hepatic insulin resistance in PPARα knockout mice was not resolved, but it is likely not related to TRB3 and rather caused by fatty acid accumulation as a result of impaired FAO." (PMID 20936117, 2010). "Notably, global Pparα-knockout mice exhibit exacerbated MASH but not insulin resistance, highlighting the complexity of the role of PPARα." (PMID 40389836, 2025). "This is thought to be because HF diet feeding was associated with increased fatty acid oxidation and decreased glucose utilization in WT mice, whereas PPARα−/− mice showed decreased fatty acid oxidation and increased glucose utilization, and, thus, no insulin resistance." (PMID 36140300, 2022). "However, PPARα knockout also shows protective function on insulin resistance whereas fibrates do not seem to improve glucose homeostasis in humans, making it confusing what role PPARα plays in glucose homeostasis." (PMID 36589809, 2022).
Insulin resistance (continued). "A lack of PPARα activation, secondary to reduced levels of adiponectin, may provide a potential mechanism for increased insulin resistance in the t-10, c-12 CLA supplemented mice." (PMID 23285120, 2012). "The gene expression of PPARγ and its target genes CD36, LDL in whitefat tissue, and PPARα and its target gene ACO in liver were also elevated in CE-treatedDIO mice indicating that CE may act as a dual activator of PPARγ and PPARαresulting in improved insulin resistance and lowered serum lipids." (PMID 19096709, 2008). "Therefore, we conclude that supplementation with palmitoleic acid but not with oleic acid can attenuate insulin resistance, liver damage, and inflammation induced by a HFD via mechanisms that do not depend on PPARα." (PMID 25147439, 2014). "Additionally, PPARα activation could promote FAO, lipolysis, and adipocyte differentiation in adipocytes and improve insulin resistance without adipocyte lipid accumulation." (PMID 30622558, 2018).
diabetes (405 papers, 2005 to 2026). "In particular, diabetes was associated with significant alterations in fatty acid metabolism, notably through increased expression of PPARα in the DM_CKD group." (PMID 41419687, 2026). "The growing body of evidence positions PPARα activation as a viable therapeutic target for a spectrum of pathologies, including cardiovascular diseases, dyslipidaemia, diabetes, and its associated sequelae, notably DR." (PMID 39941353, 2025). "In cardiac and skeletal muscles in diabetic rats, PPARα was downregulated potentially as protection against cardiac hypertrophy and due to the chronic inflammatory state associated with diabetes, where elevated cytokines act as inhibitors of PPARα expression." (PMID 40004135, 2025). "As diabetes and metabolic diseases are often associated with high blood glucose and lipid levels, drugs that activate both PPARα/γ are included." (PMID 39040675, 2024). "Our previous study has shown that diabetes-induced downregulation of PPARα in the retina plays a key pathogenic role in retinal oxidative stress and inflammation in diabetic retinopathy." (PMID 36943878, 2023). "Conversely, the expression of PPARA, which encodes the therapeutic target of fenofibrate — a clinical diabetes treatment — was marginally downregulated (log2 FC = –0.44)." (PMID 37781924, 2023). "A previous study indicated that the activation of peroxisome proliferator-activated receptor alpha (PPARα) via interacting with the aryl hydrocarbon receptor is a potential biological mechanism of the association between PCBs and diabetes." (PMID 35578291, 2022). "Drugs targeting PPARα, such as fibrates, have been developed and used in clinical applications for a long time." (PMID 34867358, 2021). "Knockout of PPARα expression aggravates retinal microvascular damage, overexpression of PPARα reduces retinal vascular leakage and retinal inflammation caused by diabetes, and alleviates retinal neovascularization in diabetic retinopathy." (PMID 35004756, 2021). "Changes in TG following fibrate treatment appear to be regulated by PPARα polymorphisms, as shown in the Diabetes Atherosclerosis Intervention Study." (PMID 31489930, 2019). "Nonetheless, both PPARα deficiency and Ex4 treatment significantly lowered diabetes‐induced heart size increase, HW/TL, and collagen deposition." (PMID 29659121, 2018). "More particularly, PPARα rs4253728G > A SNP has been associated with the risk of developing Post-Transplantation Diabetes Mellitus in patients treated with Tac." (PMID 28642710, 2017). "Polymorphisms of PPARγ and PPARα have also been described and found to be associated with disorders of hyperlipidemia, glucose homeostasis, and diabetes." (PMID 28781590, 2017). "Three PPAR receptor isotypes have been characterized (PPARα, β/δ, γ) and associated with different disease conditions, including diabetes, cancer and rheumatoid arthritis." (PMID 24015316, 2013). "Insulin resistance and diabetes mellitus cause a shift of myocardial energy metabolism away from glucose and toward increased reliance on fatty acids that is driven in part by activation of PPARα." (PMID 20838448, 2010). "As diabetes and metabolic diseases are often associated with high blood glucose and lipid levels, drugs that activate both PPARα/γ would be a logical approach." (PMID 18355413, 2008). "Genetic variation at the PPARA locus is important in determining cardiovascular risk in both male and female patients with diabetes." (PMID 16309557, 2005). "Microglia-specific PPARα deletion exacerbates retinal pericyte loss in diabetes." (PMID 40265403, 2025). "In addition, we identified PPARα as a key regulator of mitochondrial function in the cornea and found that diabetes-induced PPARα downregulation plays a pathogenic role in mitochondrial dysfunction and impaired wound healing in the cornea." (PMID 36943878, 2023).
diabetes (continued). "In conclusion, the present study identified for the first time that PPARα serves as an important regulator of mitochondrial function in the corneal epithelium, and diabetes-induced PPARα downregulation plays a pathogenic role in wound healing deficiency in the diabetic cornea." (PMID 36943878, 2023). "As for PPARα, also PPARγ variants modulate the risk for diabetes and cardiovascular events." (PMID 36768666, 2023). "Our previous study demonstrated that PPARα alleviated retinal pericyte loss in diabetes." (PMID 36497130, 2022). "We could not measure ceramides or sulfatides, sphingolipid fractions that are modulated by PPARα and appear to be associated with diabetes." (PMID 36209101, 2022). "Interestingly, microglia-specific Pparα overexpression (PCTG) alleviated diabetes-induced pericyte loss." (PMID 36497130, 2022). "Moreover, in diabetes, PPARα downregulation was associated with endothelial progenitor cell deficiency and inadequate retinal vascular repair." (PMID 33581416, 2021). "Nevertheless, two large-scale clinical trials known as the Fenofibrate Intervention and Event Lowering in Diabetes (FIELD) and Action to Control Cardiovascular Risk in Diabetes (ACCORD) studies have shown that the PPARα-agonist fenofibrate slows the progression of DR." (PMID 32977483, 2020). "The effect of PPARα polymorphisms on diabetes is controversial." (PMID 31489930, 2019). "For example, we have shown that treatment with the PPARα agonist, gemfibrozil (100 mg/kg/day), is able to attenuate albuminuria, glomerulosclerosis, tubulointerstitial expansion, and collagen IV deposition associated with streptozotocin-induced diabetes." (PMID 22448165, 2012). "A recent study showed that the cardiac phenotype induced by PPARα overexpression mimics that caused by diabetes mellitus, and this proved the activation of PPARα/PGC1α signaling to be one independent mechanism to contribute to substrate switching and diabetic cardiomyopathy." (PMID 23226270, 2012). "In diabetes mellitus- (DM-) associated liver disease, polydatin acts as PPARα/β signaling pathway activator through its anti-inflammatory and antioxidant effects." (PMID 36092543, 2022). "Activation of peroxisome proliferator-activated receptor alpha (PPARα) occurs in animal models of diabetes (DM) and is implicated in pathological responses to myocardial ischemia." (PMID 20838448, 2010). "Impairment of PPARα function can disrupt glucose metabolism, potentially leading to obesity, diabetes, and kidney failure." (PMID 41440041, 2025). "Traditionally, PPARA has been a therapeutic target for regulating lipid metabolism and has shown promise in the treatment of diabetes and diabetic nephropathy." (PMID 40417738, 2025). "For instance, it has been reported that USP28 deubiquitinates and stabilizes PPARα, thereby preventing mitochondrial morphological and functional defects while improving diabetic myocardial dysfunction." (PMID 41042219, 2025). "Type 2 diabetes mellitus (T2DM) rat models have demonstrated that hypoglycemic effects, insulin sensitization, antioxidant activity, and PPARA upregulation are associated." (PMID 40870685, 2025). "A PPARα-dependent effect of fenofibrate on the inhibition of monocyte activation in diabetes was also detected." (PMID 40265403, 2025). "Previous studies demonstrated more prominent retinal acellular capillary formation, pericyte dropout and exacerbated retinal neurodegeneration in PPARα−/− mice with diabetes compared to diabetic wild-type mice." (PMID 39941353, 2025). "Drugs such as pemafibrate, metformin, and GLP-1 agonists, classified as PPARα-related drugs, have exhibited effectiveness and safety in clinical studies by reducing lipid and glucose levels in patients with diabetes." (PMID 38473908, 2024). "The role of PPARα in diabetes cardiomyopathy is mainly reflected in regulating lipid metabolism and maintaining energy balance of myocardial cells." (PMID 39045049, 2024).
diabetes (continued). "Clinically, they are routinely used as therapeutic agents such as fenofibrate, a PPARα agonist, for hyperlipidaemia, as well as pioglitazone, a PPARγ agonist for diabetes." (PMID 38993197, 2024). "PPAR is a therapeutic target of thiazolidinediones (glitazones) for the treatment of diabetes, and pomegranates have an affinity for this receptor and PPARα." (PMID 39204642, 2024). "Puerarin also enhances Akt phosphorylation, reduces PPARα expression, and improves heart function after myocardial infarction in diabetes mice by regulating mitochondrial energy metabolism." (PMID 39045049, 2024). "Icariin modulation in endoplasmic reticulum stress and the stimulation of NO synthase through the PPARα/Sirt1/AMPKα pathway can significantly improve vascular endothelial function in diabetes, which seems to be a key mechanism of IR." (PMID 39768147, 2024). "Another experimental study reported that diabetes-induced kidney damage is more severe in PPARα-knockout diabetic mice." (PMID 39684861, 2024). "Considering our results, fasting- or diabetes-dependent induction of CAR is regulated by PPARα as well as HNF4α." (PMID 36835365, 2023). "Depending on fasting or diabetes conditions, PPARα is found to be induced at gene expression levels and activated to induce lipid metabolism." (PMID 36835365, 2023). "After RT-qPCR analysis, it was found that the mRNA expression of VEGFA, KDR, MAPK14, and PPARA showed significant differences between normal and diabetes mellitus mice, with a retracement after FBT treatment." (PMID 38304230, 2023). "To explore the molecular basis for the diabetes-induced mitochondrial function decline in the cornea, we evaluated the role of PPARα." (PMID 36943878, 2023). "PPAR agonists (PPARα and PPARγ) have been clinically used for many years as treatments for diabetes and dyslipidemia while mixed (PPARα/δ/γ) agonists have been evaluated for efficacy against NASH." (PMID 36817797, 2023). "Meanwhile, the decrease of PPARα is also found in various diseases including MAFLD, diabetes, Alzheimer’s disease, and cardiovascular disease, emphasizing the key role of PPARα in human diseases." (PMID 36589809, 2022). "Under streptozotocin (STZ)-induced diabetes, diabetic PCKO mice exhibited decreased electroretinography response, while diabetes-induced retinal dysfunction was alleviated in diabetic microglia-specific Pparα-transgenic (PCTG) mice." (PMID 36497130, 2022). "The present study revealed the role of PPARα in regulating retinal microglia metabolism and activation in the context of diabetes." (PMID 36497130, 2022). "Other studies showed that BCA, as an effective peroxisome proliferator-activated receptor α (PPARα) agonist, can improve the arteriosclerosis of diabetic complications by activating PPARα, which is effective in the treatment of diabetes." (PMID 36144522, 2022). "Fenofibrate, a peroxisome proliferator-activated receptor alpha agonist, has lipid-modifying effects on high triglyceride and reduces the microvascular complications of diabetes." (PMID 36760666, 2022). "These drugs are well-known peroxisome proliferator-activated receptor alpha (PPARα) agonists, and they have been increasingly nominated as promising drugs for various ischemic retinopathies with diabetes or hyperlipidemia." (PMID 35563640, 2022). "PPARα is an important therapeutic target for various types of diseases in clinics, for example, dyslipidemia, cardiovascular diseases, and diabetes." (PMID 36588740, 2022). "Conditional knockout of Pparα in the microglia aggravated, whereas conditional Pparα overexpression ameliorated diabetes-induced retinal dysfunction, suggesting the protective effect of microglial PPARα against diabetic neurodegeneration." (PMID 36497130, 2022). "The relative content of PPARα and its downstream genes were then correlated with arterial disease severity and patient diabetes status." (PMID 35783870, 2022).